MIR4643 (microRNA 4643)
Synonyms: hsa-mir-4643
Gene: MicroRNA gene on chromosome 6 (91,521,660 to 91,521,737, forward strand). Ensembl gene ENSG00000263734.
Homologues: Orthologues: chimpanzee MIR4643 (100% identical).